S100A8 (S100 calcium binding protein A8)
Diseases named in the same sentence as S100A8 in open-access papers (continued):
Sharing a sentence is not in itself a finding about the gene and the disease.
polyarticular JIA (1 paper, 2025). "Similarly, in patients with SoJIA, the serum levels of S100A8 and S100A9 are notably elevated, with a 12-fold increase in active polyarticular JIA patients and a striking 120-fold increase compared to normal controls." (PMID 39877611, 2025).
primary biliary cirrhosis (1 paper, 2012). "A potential positive role for S100A8/9 in dendritic cells has also been proposed in the context of primary biliary cirrhosis pathogenesis." (PMID 22253789, 2012).
primary sclerosing cholangitis (1 paper, 2019). "This notion can be supported by the observation of the high biliary levels of S100A8/9 in patients with primary sclerosing cholangitis." (PMID 31582902, 2019).
prostatic adenocarcinoma (1 paper, 2022). "In our previous study, urinary concentrations of S100A8/A9 and S100A12 were both significantly increased in dogs with TCC, prostatic adenocarcinoma (PCA), or UTI compared to healthy control dogs." (PMID 36411489, 2022).
prostatic diseases (1 paper, 2023). "Mean S100A8/A9+ cell counts were higher (median: 9 cells/0.01 mm2) in dogs with marked prostatitis compared to the other three groups of dogs (medians: 0–1 cell/ 0.01 mm2)." (PMID 37946179, 2023).
psychological distress (1 paper, 2024). "In addition, monitoring S100A8/S100A9 levels could lead to earlier intervention in managing psychological distress in metastatic patients, which was linked to increased inflammatory signaling." (PMID 39830522, 2024).
Pulmonary hemorrhage (1 paper, 2024). Pulmonary hemorrhage is a bleeding within the lungs. "We hypothesized that loss of Syk kinase in neutrophils would prevent the pulmonary hemorrhage and hyperinflammation observed in Ptpn6fl/fl S100A8(Cre+) mice." (PMID 39352872, 2024). "To better understand the role of NETs in the pulmonary hemorrhage we observed as a result of neutrophil Shp1 deletion, PAD4–/– mice were crossed to Ptpn6fl/fl S100A8(Cre+) and challenged with intratracheal LPS." (PMID 39352872, 2024).
pulmonary hypertension (1 paper, 2025). Increased pressure within the pulmonary circulation due to lung or heart disorder. "Various studies have demonstrated the role of S100A8/A9 in promoting inflammation, fibroblast growth, and collagen production in various lung diseases including pulmonary hypertension." (PMID 40948742, 2025). "As RAGE ligands, S100A8/A9 would be critical in regulating inflammasome pathways in pulmonary hypertension, a topic further elaborated below." (PMID 40948742, 2025). "Understanding the interactive and feedback mechanism between NLRP3 inflammasome, S100A8/A9, and GSDMD is necessary to explore their role in pulmonary hypertension." (PMID 40948742, 2025). "However, the contribution of NLRP3 inflammasome, S100A8/A9, and GSDMD as a team to pulmonary hypertension is unclear." (PMID 40948742, 2025).
pyometra (1 paper, 2015). "Overexpression of S100A8, S100A9 and S100A12 genes were detected in pyometra, particularly in the hormone-treated animals." (PMID 26222498, 2015). "SLPI, PTGS2/COX2, MMP1, S100A8, S100A9 and IL8 were among the top up-regulated genes detected in pyometra, further confirmed by external expression data." (PMID 26222498, 2015). "Thus, high levels of S100A8 and S100A9 in pyometra may be a result of tissue damage leading to amplification and/or perpetuation of the local inflammation, being an attractive therapeutic target." (PMID 26222498, 2015).
rash (1 paper, 2024). "Patients in our study had significantly higher serum S100A8/A9 levels when three or more skin regions were covered with a rash." (PMID 38672106, 2024). "Serum levels of S100A8/A9 were also higher in patients with greater skin areas covered with rash." (PMID 38672106, 2024).
respiratory depression (1 paper, 2023). A decrease in ventilation secondary to impaired signals from the central nervous system. "Mechanistically, we show that S100A8/A9 blockade inhibits local inflammation and improves endotoxemia-induced mitochondrial respiratory depression in the myocardium." (PMID 37773186, 2023).
respiratory distress syndrome (1 paper, 2013). "A role of calgranulin A/B complex in the endotoxin-induced reaction is also supported by clinical studies having related the S100A8/A9 expression with suppuratiing respiratory diseases, respiratory distress syndrome and COPD." (PMID 24237763, 2013).
respiratory failure (1 paper, 2023). The significant impairment of gas exchange within the lungs resulting in hypoxia, hypercarbia, or both, to the extent that organ tissue perfusion is severely compromised. "Patients with kidney, liver, cerebral, coagulation, circulation, and respiratory failure had elevated plasma S100A8 and S100A9 than those without these conditions, as well as those with bacterial infections." (PMID 37469934, 2023).
retinal degeneration (1 paper, 2023). Degeneration of the retina. "Choroidal DCs express higher levels of S100A8/9.Experimental model: increased levels of MHC class II+ DCs in a murine model of light-induced retinal degeneration." (PMID 37443742, 2023).
salivary gland tumors (1 paper, 2024). "Some of the identified peptides were derived from proteins previously suggested as potential biomarkers of salivary gland tumors (ANXA1, BPIFA2, FGB, GAPDH, HSPB1, IGHG1, VIM) or tumors of other tissues or organs (SERPINA1, APOA2, CSTB, GSTP1, S100A8, S100A9, TPI1)." (PMID 39201484, 2024).
Salmonella Infections (1 paper, 2015). Infections with bacteria of the genus SALMONELLA. "The functional role of S100A8/A9 in the host defense against murine Salmonella infection was limited however, given the fact that S100A9-/- mice were indistinguishable from WT mice with respect to survival, bacterial organ counts and inflammatory responses." (PMID 25860480, 2015). "In the present study we investigated the role of S100A8/A9 during invasive Salmonella infection and observed a marked increase of this protein in patients with typhoid fever, which correlates with disease stage and severity." (PMID 25860480, 2015). "In a murine Salmonella infection model the levels of S100A8/A9 were also elevated but S100A8/A9 deficiency in mice did not influence bacterial growth and dissemination, organ damage or mortality." (PMID 25860480, 2015).
schistosomiasis (1 paper, 2024). An infectious disease caused by parasitic trematodes of the genus Schistosoma that colonize human blood vessels and release eggs that can cause granulomatous reactions leading to acute (swimmer's itch or acute schistosomiasis syndrome) or chronic disease. "Although the roles of S100A8 and S100A11 have not yet been elucidated in schistosomiasis, the S100A proteins are known as effector molecules that can block the development of several invading pathogens such as Salmonella typhimurium and Staphylococcus aureus." (PMID 39398025, 2024).
small cell lung carcinoma (1 paper, 2025). Small cell lung cancer (SCLC) is a highly aggressive malignant neoplasm, accounting for 10-15% of lung cancer cases, characterized byrapid growth, and early metastasis. "S100A8/A9 plays a role in metastasis, as shown in SBC5 (small cell lung carcinoma cell line) invasion via the S100A8/A9-IL6R-TLR4 pathway, a key mechanism facilitating osteolytic activity in bone metastases." (PMID 41164170, 2025).
staphylococcus aureus infection (1 paper, 2023). An infectious process in which the bacteria Staphylococcus aureus is present. "Consistent with our result, the antimicrobial peptides S100A8, S100A9, and CATHL\H4 were highly expressed in milk exosomes after Staphylococcus aureus infection." (PMID 36611779, 2023).
Stillbirth (1 paper, 2019). Death of the fetus in utero after at least 22 weeks of gestation. "The CXCL8 and PF4 are located within regions associated with calving-to-conception interval or calving-to-first-estrous interval, while S100A8 is within a stillbirth QTL region." (PMID 31374089, 2019).
T-cell leukemia (1 paper, 2017). A malignant disease of the T-lymphocytes in the bone marrow, thymus, and/or blood. "Preclinical study has demonstrated S100A8 promoted cell growth of murine B-cell leukemia (BJAB) and human T-cell leukemia (Jurkat) lines." (PMID 28183295, 2017).
thoracic aortic aneurysm (1 paper, 2024). An aneurysm formed in the wall of the proximal portion of the descending aorta proceeding from the arch of the aorta. "Many S100 family proteins, such as S100A8, S100A9, and S100A12, play a key role in thoracic aortic aneurysms and other cardiovascular diseases 40-42." (PMID 38164183, 2024).
transitional cell carcinoma (1 paper, 2015). A malignant neoplasm arising from the transitional epithelium, usually affecting the urinary bladder, ureter, or renal pelvis. "In the present study, the serum levels of S100A8/A9 was compared in different groups of patients with RCC, transitional cell carcinoma (TCC) in the kidney, benign lesions in the kidney and normal controls." (PMID 25673070, 2015).
tuberculous pleurisy (1 paper, 2022). "Biomarker studies have also determined that S100A8 is differentially upregulated in patients with tuberculous pleurisy compared to patients with cancer." (PMID 36003300, 2022).
typhoid fever (1 paper, 2015). A bacterial infectious disorder contracted by consumption of food or drink contaminated with Salmonella typhi. "Typhoid fever patients demonstrated a marked increase of S100A8/A9 in acute phase plasma and feces and this increases correlated with duration of fever prior to admission." (PMID 25860480, 2015). "The role and importance of the elevated levels of S100A8/A9 in human typhoid fever requires further study." (PMID 25860480, 2015). "Although S. Typhimurium is widely used in murine studies as a surrogate for S. Typhi and levels of S100A8/A9 were both elevated in human typhoid patients and mice infected with S. Typhimurium, Salmonella spp." (PMID 25860480, 2015). "In this study we aimed to characterize the expression and function of S100A8/A9 in typhoid fever, linking observational studies in patients with functional studies in S100A9-/- mice." (PMID 25860480, 2015). "We have determined the levels of S100A8/A9 in patients with acute typhoid fever and during convalescence." (PMID 25860480, 2015). "We aimed to characterize the expression and function of S100A8/A9 in patients with typhoid fever and in a murine invasive Salmonella model." (PMID 25860480, 2015). "Other potential explanations for the observed high levels of S100A8/A9 in typhoid fever patients could be disturbances in controlled release of these proteins or defective clearance of the proteins." (PMID 25860480, 2015). "The expression and function of S100A8/A9 in typhoid fever caused by S. Typhi has not been studied before." (PMID 25860480, 2015). "In agreement with the data obtained in patients with typhoid fever, WT mice infected with different dosages of S. Typhimurium (105 and 106 CFU) showed increased levels of S100A8/A9 in different compartments corresponding with stage and severity of disease." (PMID 25860480, 2015). "It should be emphasized that given the disadvantages of the Salmonella mouse model, negative results from the murine model do not exclude a functional role of S100A8/A9 in human typhoid fever." (PMID 25860480, 2015).
uterine cancer (1 paper, 2023). Primary or metastatic malignant neoplasm involving the uterine corpus and/or the cervix. "Notably, analysis of TCGA Pan-Cancer Atlas showed a consistent positive correlation between SERPINB3 and CXCL1, CXCL8, S100A8, and S100A9 across multiple tumor types including bladder, breast, head and neck, lung, prostate, and uterine cancers." (PMID 37279067, 2023).
uterine carcinosarcoma (1 paper, 2022). A usually aggressive malignant neoplasm arising from the uterine corpus and less often the cervix. "For instance, S100A4/non-muscle myosin II signaling has been associated with epithelial–mesenchymal transition and stemness in uterine carcinosarcoma, while the inhibition of S100A8 expression is reported to promote apoptosis through the suppression of AKT phosphorylation." (PMID 35042454, 2022).
vaginal infections (1 paper, 2024). "Researchers have further elucidated the biological role of S100 alert proteins in the pathogenesis of C. albicans vaginal infections, observing that antibody neutralization of S100A8 and S100A9 affects the chemotactic activity of neutrophil in vaginal lavage." (PMID 38794163, 2024).
venous ulcer (1 paper, 2025). "In a different study, fibronectin was shown to be elevated, but S100A8 and S100A9 were decreased in chronic venous ulcer fluids compared to acute wound fluid." (PMID 40342218, 2025).
viral meningitis (1 paper, 2025). Inflammation of the membranes surrounding the brain and spinal cord due to a viral infection. "In contrast, patients with viral meningitis have a plasma protein profile dominated by acute-phase and pro-inflammatory markers (e.g., CRP, S100A8, S100A9) and immunoglobulin production." (PMID 41145505, 2025).
vivax malaria (1 paper, 2015). "Therefore, S100A8 in vivax malaria appears to promote its immune escape, as elevations in PD-L1 on the iDCs surface by synthetic S100A8 promotes Treg cell induction greater than that observed in controls." (PMID 26438270, 2015).
volvulus (1 paper, 2018). "Moreover, the mean urinary levels of S100A8/A9 were higher than normal in the final diagnosis except in volvulus." (PMID 30057651, 2018).
α-synucleinopathies (1 paper, 2024). "Mechanistically, the heterodimeric protein S100A8/A9 may be the downstream target of Usp14 deficiency in female mouse models of α-synucleinopathies." (PMID 38780644, 2024). "Mechanistically, Usp14 deficiency enhanced the expressions of heterodimeric protein S100A8/A9 in the substantia nigra (SN) of mouse models with α-synucleinopathies." (PMID 38780644, 2024).
infection (602 papers, 2005 to 2026). The state of being infected such as from the introduction of a foreign agent such as serum, vaccine, antigenic substance or organism. "Overexpression recombinant lentivirus and short hairpin RNA-encoding lentivirus were used to overexpress and knock down S100A8 in HT-1376 cells via infection." (PMID 39895787, 2025). "Nonetheless, the present results underscore the importance of future clinical studies carefully monitoring for signs of infection and evaluating the risk–benefit ratio of S100A8/S100A9 inhibition in patients with GLM." (PMID 41476978, 2025). "S100A8/A9 belong to the family of danger-associated molecular patterns that are induced upon infection, injury or inflammation to initiate the first rapid inflammatory response." (PMID 39337466, 2024). "For example, S100A8 encodes an alarmin protein that mediates host pro-inflammatory responses during infection." (PMID 39350339, 2024). "We found that in comparison to the WT, infection with the ▵vapC12 strain enhanced the expression of genes that encode proteins implicated in neutrophil-mediated immunity in the host (Cxcl2, Trem1, S100A8/A9 and Ccl3)." (PMID 38515752, 2024). "S100A8 and A9 belong to the family of danger associated molecular patterns that are rapidly induced upon infection, injury or inflammation initiating the first rapid inflammatory response." (PMID 39337466, 2024). "infection causes cardiac dysfunction by either directly dissemination into the heart or due to S100A8/A9-medated activation of the host immune response." (PMID 37624851, 2023). "S100A8 is also associated with acute lung injury, being secreted by degranulating neutrophils and bronchial epithelium during infection/inflammation." (PMID 37474963, 2023). "infection, S100A8/A9 deficiency significantly enhanced mouse morbidity and mortality, and that S100A8A/9 deficiency promotes bacterial dissemination to the heart resulting in severe cardiac dysfunction." (PMID 37624851, 2023). "infection studies using a global S100a9 knockout (deficient of both S100A8 and S100A9 proteins) and wild type (WT) mice." (PMID 37624851, 2023). "infection induced release of S100A8/9 is double-edged, providing increased risk for cardiac dysfunction yet limiting P. a." (PMID 37624851, 2023). "Inflammatory macrophages (cluster 3) exhibited a highly interconnected set of unique DEGs encoding for neutrophil granule proteins such as s100a8 and s100a9 that are upregulated in neutrophils in response to infection." (PMID 38149246, 2023). "Application of S100A8/A9 immediately after infection and after 11 h led to a complete loss of the differences between S100A9−/− and WT mice in neutrophil recruitment to the intravascular, interstitial and alveolar compartments of the lung." (PMID 36497202, 2022). "In DENV, the potential pathogenic role of neutrophils against the infection has already been shown, suggesting a possible connection between the high expression of S100A8/9 at Day −2 and DENV pathogenesis." (PMID 35345453, 2022). "Correspondingly, transcription of Reg3γ as well as the genes encoding the antimicrobial factors S100a8 and S100a9 was also strongly induced (100-fold) during infection, potentially to promote host defense." (PMID 31848276, 2019). "By triggering TLR4- or RAGE-mediated multiple inflammatory pathways, S100A8/A9 plays an important role in protecting the body from pathogenic infection." (PMID 29942307, 2018). "Presumably associated with PMNs' infiltration, s100a8 and s100a9 expressions in the lung mainly occurred at 3 days post–infection." (PMID 21423669, 2011). "The expression levels of Lcn2, which encodes for the antimicrobial protein lipocalin-2, and of S100a8 and S100a9, whose gene products together form the antimicrobial protein calprotectin, were increased during infection but were comparable between WT mice and Il22−/− mice." (PMID 38557196, 2024).